CDC42 (cell division cycle 42)
Diseases named in the same sentence as CDC42 in open-access papers (continued):
Sharing a sentence is not in itself a finding about the gene and the disease.
colorectal cancer (continued). "In keeping with the results presented here, one of these molecules, AZA197 suppressed primary colon cancer growth in vivo and prolonged survival in SW620 tumor xenografts, indicating the therapeutic potential of this inhibitor based on targeting CDC42 GTPase activity in colorectal cancer." (PMID 28460460, 2017). "The pro-oncogenic role of CDC42 in this tumor type has been further demonstrated in several independent studies, in which the overexpression or silencing of CDC42 either in vitro or in vivo showed oncogenic-phenotypic effects in different colorectal cancer cell lines and mouse models." (PMID 28460460, 2017). "The homeostatic function of miR-18a within the miR-17-92 cluster in colorectal cancer cells may be achieved through suppression of CDC42 and the PI3K pathway." (PMID 25379703, 2014). "Based on these findings, we hypothesized that inhibition of Cdc42 might be effective for the treatment of colorectal cancer." (PMID 24279335, 2013). "Furthermore, expression of constitutively active Cdc42 significantly increased filopodia formation and cell spread in colorectal cancer cells, which is in line with our findings." (PMID 24279335, 2013). "Moreover, Cdc42 was found to be over-expressed with high incidence in colorectal cancer samples suggesting a potential role for Cdc42 in tumor development." (PMID 24279335, 2013). "We then assessed whether invasiveness and the level of active Rho GTPases, which are key components of the invasive machinery, were correlated by comparing the level of GTP-bound Cdc42, Rac1 and RhoA in the different colorectal cancer cell lines." (PMID 23144867, 2012). "In addition, miR-330 regulates the proliferation of colorectal cancer cells by targeting CDC42." (PMID 33152231, 2021). "Moreover, miR-185 is a negative regulator of RhoA and CDC42, and could inhibit the proliferation and invasion of human colorectal cancer cells." (PMID 33152231, 2021). "While, in colorectal cancer cells, ectopic miR-137 expression also could arrest cell cycle, repress cell growth, and inhibit cell invasion through targeting cell division control protein 42 homolog (Cdc42)." (PMID 26545111, 2015). "Data from patients showing that Cdc42 is overexpressed with high incidence in colorectal adenocarcinoma biopsies and the findings in this study, support the notion that Cdc42 inhibition could be used as a therapeutic strategy to fight colorectal cancer." (PMID 24279335, 2013). "While our study's findings suggest the potential prognostic value of the CDC42, TAGLN, and GSN genes in colonic polyp lesions and colorectal cancer, it is essential to acknowledge certain limitations." (PMID 37365287, 2023). "In colorectal cancer, DIAPH2 expression stimulates actin nucleation and microtubule stabilization, potentially controlling the cell cycle in a CDC42-independent manner." (PMID 33302475, 2020). "Cdc42 activity specific inhibitor (CASIN) was identified in cell-based assays, and inhibits Cdc42 interaction with intersectin, leading to suppression of colorectal cancer malignant progression." (PMID 32392742, 2020). "Studies have also suggested that miR-185 can downregulate the activity and function of RhoA and Cdc42 by targeting sites in the RhoA and Cdc42 3’UTR, which then can suppress the proliferation and invasiveness of the colorectal cancer cells." (PMID 29596304, 2018). "Thus, CDC42 could be used as a therapeutic target for selective colorectal cancer intervention." (PMID 28460460, 2017). "Combined treatment with PDGF to restore Cdc42 and Rac1 function and with Y27632 to inhibit ROCK synergistically reduced the invasive potential of such colorectal cancer cells." (PMID 23144867, 2012). "We report that the high invasive potential of colorectal cancer cells with elevated blebbing activity correlates with both increased ROCK activation and decreased Cdc42 and Rac1 activities." (PMID 23144867, 2012).
colorectal cancer (continued). "In addition, miR-84 suppressed cell proliferation, migration, and metastasis in renal cell carcinoma and colorectal cancer by targeting and interacting with RAB23 and KRAS/CDC42 axis, respectively." (PMID 33817254, 2020). "However, activation of Cdc42 can induce cell adhesion and it has been recently shown that activated Cdc42 increases SW480 colorectal cancer cell adhesion, migration and invasion." (PMID 24279335, 2013). "We conclude that, in the tested colorectal cancer cell lines, the level of active Cdc42 and Rac1, but not of RhoA, is inversely correlated with the invasiveness of such cells (respective p values: 0.0008, 0.0003 and 0.134)." (PMID 23144867, 2012). "We show that the ability to invade of these colorectal cancer cell lines is correlated with a marked decrease in Cdc42 and Rac1 activity and an increase in ROCK, but not RhoA, activity." (PMID 23144867, 2012). "Examples discussed in this review include Cdc42, Rac1, RhoA, RhoC and RhoH activation of oncogenic STAT3, and in some cases STAT5, in a range of cancers including but not limited to: breast, bladder, gastric, cervical, myeloid, pancreatic, hepatocellular, head and neck, and colorectal cancer." (PMID 32915198, 2020).
melanoma (48 papers, 2011 to 2025). A malignant, usually aggressive tumor composed of atypical, neoplastic melanocytes. "In the melanoma validation cohort, patients with CDC42 gene set mutations had significantly longer PFS and OS (OS: p = 1.16E‐2, HR = 0.38, 95% CI = 0.17–0.83; PFS: p = 1.18E‐2, HR = 0.49, 95% CI = 0.28–0.86)." (PMID 39791593, 2025). "Recently, an activating mutation in Cdc42, a Rho family GTPase, was found in a patient sample of melanoma." (PMID 37114375, 2023). "Our work is the first to show that Cdc42(G12V) enhances the carcinogenic potential of melanoma cells that harbour a BRAF mutation, the most common mutation seen in melanoma." (PMID 37114375, 2023). "The Cdc42(G12V) mutation was identified in melanoma samples during whole exome sequencing of patient samples." (PMID 37114375, 2023). "For the Cdc42-active Dbl proteins, oesophageal squamous cell carcinoma, endometrial carcinoma and melanoma show the highest mutational alterations." (PMID 34196668, 2021). "Consistent with an important role of Cdc42‐GTPase in regulating the invasive migration of BRAFi‐R melanoma cells, ML141 treatment caused a significant reduction of the migration and invasion of the HTB63‐R cells compared with the vehicle‐treated control cells." (PMID 30582770, 2019). "Based on this deficiency and our present findings that BRAFi‐R melanoma cells exhibit increased migration and invasion, we investigated Cdc42 activities in these BRAFi‐R cells." (PMID 30582770, 2019). "The Rho GTPase Cdc42 has been implicated as a central molecule in stimulating invadopodia in numerous cancer cell lines, including melanoma, glioblastoma, breast, and pancreatic tumor derived cells." (PMID 26765257, 2016). "Although relatively few Cdc42 oncogenic mutations have been reported in cancer, the overexpression of Cdc42 is observed in several types of cancers, such as breast, colorectal, esophageal, gastric, lung, melanoma, ovarian, pancreatic, and testicular cancers." (PMID 38612766, 2024). "Cdc42(G12V) has been implicated as a driver mutation in melanoma necessary for invasion of melanoma cells Furthermore, increased Cdc42 expression has been associated with a poorer prognosis and its effectors are associated with increased resistance to BRAF inhibitors." (PMID 37114375, 2023). "Our present study sought to determine whether PI3K was a crucial downstream partner for Cdc42 in a melanoma cells line with a BRAF mutation, which is the most common mutation in cutaneous melanoma." (PMID 37114375, 2023). "One of these studies also identified the Cdc42(G12V) mutation in melanoma samples." (PMID 37114375, 2023). "To analyze whether impaired Cdc42 signaling is responsible for the reduced invasion caused by WNT5A knockdown in these melanoma cells, we stimulated the cells with a Cdc42 and Rac1 activator." (PMID 33969605, 2021). "This anti-vascular effect was not limited to skin, as CDC42 interaction inhibitors blocked melanoma tumor vascularization and inhibited tumor growth to a similar degree as Braf inhibitors." (PMID 40950721, 2025). "Taken together, the data from this study suggests that PI3K is an important effector protein downstream of activated Cdc42 in A375 human melanoma cell lines." (PMID 37114375, 2023). "In this work, we show that Cdc42(G12V) drives cancer phenotypes in BRAF mutant A375 melanoma cells, including proliferation, anchorage-independent growth, migration, and invasion." (PMID 37114375, 2023). "ARN22089 is a novel compound that has been reported to block the interaction between Cdc42 GTPases and their effectors in mouse melanoma models and in patient-derived xenografts in vivo." (PMID 37174724, 2023). "Because we were able to suppress even the constitutively activated Cdc42(G12V) protein when we inhibited PI3K, our study strongly suggests that PI3K is an effector of Cdc42 in this human melanoma cell line." (PMID 37114375, 2023).
melanoma (continued). "Only two genes, ITSN2 and ARHGEF9, both of which are CDC42 GEFs, regulate melanoma shape on both soft and stiff materials." (PMID 36039362, 2022). "We found that reduced WNT5A signaling significantly inhibits Cdc42 activity and melanoma cell invasion in a spheroid invasion assay." (PMID 33969605, 2021). "Taken together, our results suggest that WNT5A downregulation inhibits Cdc42‐dependent melanoma cell invasion in 3D collagen matrices." (PMID 33969605, 2021). "Using the 3D melanoma model prepared in this way, the reduction in the expression of Rho-family GTPase (Cdc42/Rac1/RhoA) protein by NX-5 treatment was confirmed by immunohistochemical staining." (PMID 34201921, 2021). "Immunohistochemistry showed that Cdc42, Rac1, and RhoA were constitutively expressed in the nuclei of melanoma cells of the untreated group, and NX-5 treatment decreased their expression." (PMID 34201921, 2021). "In conclusion, while WNT5A‐deficient melanoma cells exhibit reduced Cdc42 signaling and invasion, we also identified a counteracting response to this reduction in invasion in BRAF wild‐type and BRAFV600 mutated melanoma cells treated with a BRAF inhibitor." (PMID 33969605, 2021). "In melanoma, Cdc42 contributes both amoeboid and mesenchymal movement and overall tumor cell invasion." (PMID 34201921, 2021). "Immunohistochemistry for our 3D melanoma model showed that Cdc42, Rac1, and RhoA were constitutively expressed in the nuclei of melanoma cells of the untreated group, and NX-5 treatment decreased their expression." (PMID 34201921, 2021). "In vitro studies have revealed that CDC42 is required downstream of the RhoGEF DOCK10 to favor amoeboid migration in melanoma cells." (PMID 34503171, 2021). "WNT5A knockdown impaired Rho GTPase Cdc42 activity, resulting in reduced invasion of amoeboid and mesenchymal melanoma cells." (PMID 33969605, 2021). "The first evidence of the role of ET-1 in invadopodia formation has been highlighted in human melanoma cells, where ET-1 through Gi activates Cdc42 GTPase while decreasing RhoA." (PMID 33178698, 2020). "Accordingly, CDC42 expression was suggested as a prognostic marker of shorter OS in melanoma patients." (PMID 33072757, 2020). "In the last decades, the role of Cdc42, Rac, and RhoA, the best-characterized members of this family, was extensively explored in relation to melanoma cell motility." (PMID 33072757, 2020). "This impaired invasive migration of BRAFi‐R melanoma cells correlated well with the reduction in Cdc42‐GTPase activity and alterations of the actin cytoskeleton in these cells." (PMID 30582770, 2019). "In search of regulators of the cytoskeleton in BRAFi‐R melanoma cells, we found that the induction of BRAFi resistance increases the activity of the small GTPase Cdc42 in melanoma cells." (PMID 30582770, 2019). "To investigate the importance of this signalling molecule, we next blocked IL‐6 and WNT5A signalling as well as Cdc42‐GTPase activation itself in BRAFi‐R melanoma cells and studied how these treatments affected the cellular actin network." (PMID 30582770, 2019). "Based on our present observations, we conclude that simultaneous inhibition of IL‐6 and WNT5A signalling effectively obstruct Cdc42‐dependent migration and invasion of BRAFi‐R melanoma cells." (PMID 30582770, 2019). "CDC42 is highly expressed in various types of human cancers, such as melanoma, breast, colon cancer, as well as hepatocellular carcinoma." (PMID 28282856, 2017). "While previously published studies have defined a role for Cdc42 in regulating melanoma cell movement, this study represents the first identification of a specific Cdc42 signaling network that cooperates with BRAF to regulate melanocyte growth in vivo." (PMID 28753606, 2017). "This interpretation is supported by the data that silencing Cdc42 in control melanoma cells elevated their nuclear and cytoplasmic transmigration to the extent similar to that of TRCs." (PMID 26787224, 2016).
melanoma (continued). "To investigate the involvement of Cdc42 in the present WNT5A induced effects, we first confirmed that rWNT5A indeed activated Cdc42 also in malignant melanoma Mewo cells." (PMID 24766647, 2014). "We first sought to determine whether wild-type Cdc42 and/or Cdc42(G12V) could increase proliferation in A375 melanoma cells." (PMID 37114375, 2023). "In this work, we hypothesized that PI3K might be an important target downstream of activated Cdc42 in melanoma cells." (PMID 37114375, 2023). "Future studies will determine whether other identified effectors can be used as targets downstream of Cdc42 in melanoma cell lines." (PMID 37114375, 2023). "Furthermore, the use of a PI3K inhibitor in cells overexpressing Cdc42(G12V) can decrease proliferation, anchorage-independent growth, migration, and invasion of A375 melanoma cells." (PMID 37114375, 2023). "Once we established that Cdc42(G12V) was able to increase the migration of melanoma cells, we wanted to investigate whether PI3K was required downstream of Cdc42(G12V) for this particular metastatic phenotype." (PMID 37114375, 2023). "Because we found that both wild-type Cdc42 and Cdc4(G12V) greatly enhanced A375 melanoma cell proliferation, we wanted to see if we could decrease this growth after treatment with LY294002." (PMID 37114375, 2023). "We hypothesized that inhibiting activated Cdc42 in melanoma cells by inhibiting PI3K could inhibit activated Cdc42-driven phenotypes such as proliferation, 3D cell growth, invasion, and migration." (PMID 37114375, 2023). "In addition, NX-5 has the potential to have similar inhibitory effects as Cdc42 inhibitor, Rac1 inhibitor, and RhoA inhibitor in human melanoma cell lines." (PMID 34201921, 2021). "We then explored whether the reduced activity of Cdc42 is responsible for the impaired invasion of melanoma cells upon reduced WNT5A expression through gain‐of‐function experiments with the Cdc42 and Rac1 activator II." (PMID 33969605, 2021). "Additionally, NX-5 (20 μM) treatment significantly decreased the mRNA and protein expression levels of Cdc42, Rac1, and RhoA in melanoma cells compared with the untreated group (p < 0.001 and p < 0.05, respectively)." (PMID 34201921, 2021). "However, deletion of DOCK10, PAK2 or N-WASP, which all contribute to amoeboid migration in melanoma cells, also resulted in an elongated morphology, implicating more Cdc42 pathways in mesenchymal migration." (PMID 34196668, 2021). "Moreover, CDC42 contributes to the release of exosomes when malignant melanoma cells are treated with WNT5A." (PMID 34503171, 2021). "A similar mechanism has been demonstrated in melanoma cells through balancing Cdc42/RhoA activity." (PMID 33178698, 2020). "Furthermore, the expression of Cdc42 constitutively active mutants induces cells to adopt a rounded shape increasing melanoma cell invasion and consequently allowing a mesenchymal–amoeboid transition." (PMID 33072757, 2020). "To confirm that Cdc42‐GTPase could promote migration and invasion in BRAFi‐R melanoma cells, we exposed HTB63‐R cells to a specific‐Cdc42‐GTPase inhibitor, for example ML141." (PMID 30582770, 2019). "The small GTPase Cdc42 has been reported to be an important regulator of melanoma cell invasion." (PMID 30582770, 2019). "Next, we investigated whether combined inhibition of both IL‐6 and WNT5A signalling had any effect on Cdc42‐GTPase or Rac1‐GTPase activity in BRAFi‐R melanoma cells." (PMID 30582770, 2019). "Cdc42 is mainly related to the formation of thin and short filopodia in melanoma cells." (PMID 28404912, 2017). "We also observed that WISP-1 inhibited phosphorylation of RhoA/Rac1/CDC42 in C8161 melanoma cells." (PMID 27813493, 2016). "Importantly, when Cdc42 is silenced in the stiff control melanoma cells, they elevated their transmigration rates to the similar levels as the TRCs, suggesting that high Cdc42 in those cells impede 3D transmigration through narrow pores." (PMID 26787224, 2016).